MRTFB (myocardin related transcription factor B)
Description:
Acts as a transcriptional coactivator of serum response factor (SRF). Required for skeletal myogenic differentiation.
Synonyms: MRTF-B; MKL2; FLJ31823; NPD001
Tractability: PROTAC: UniProt records ubiquitination sites on it; ubiquitination databases record sites on it.
Gene: Protein-coding gene on chromosome 16 (14,071,058 to 14,266,778, forward strand). Ensembl gene ENSG00000186260.
Subcellular location: Nucleus
Subcellular location (Human Protein Atlas): Nuclear speckles
Gene Ontology:
Molecular function: cadherin binding; protein binding; transcription coactivator activity
Biological process: positive regulation of miRNA transcription; positive regulation of striated muscle tissue development; positive regulation of transcription by RNA polymerase II; smooth muscle cell differentiation
Cellular component: nuclear speck; nucleus
Genetic constraint (gnomAD): Loss-of-function variants: 24 observed, 96.09 expected, observed/expected ratio (o/e) 0.25, 90% interval 0.18 to 0.35. The upper end of that interval is the gene's LOEUF score, 0.35, which puts it in group 1 of 6, group 1 being the genes least tolerant of losing a copy. Missense variants: 1,216 observed, 1,326.8 expected, observed/expected ratio (o/e) 0.92, 90% interval 0.87 to 0.96. Synonymous variants: 515 observed, 522.77 expected, observed/expected ratio (o/e) 0.99, 90% interval 0.92 to 1.06.
Homologues: Orthologues: chimpanzee MRTFB (100% identical), macaque MRTFB (98% identical), dog MRTFB (89% identical), rabbit MRTFB (86% identical), guinea pig MRTFB (85% identical), pig MRTFB (85% identical), mouse Mrtfb (84% identical), rat Mrtfb (83% identical), tropical clawed frog mrtfb (61% identical), zebrafish mrtfba (46% identical), zebrafish mrtfbb (41% identical), Caenorhabditis elegans pqn-62 (18% identical), and 1 more. Paralogues in human: MRTFA (42% identical), MYOCD (32% identical).
Diseases named in the same sentence as MRTFB in open-access papers:
MRTFB is named in the same sentence as 32 diseases in open-access papers, as found by Europe PMC text mining. Sharing a sentence is not in itself a finding about the gene and the disease. The quoted sentences say what the papers report.
autism spectrum disorder (3 papers, 2018 to 2022). A spectrum of developmental disorders that includes autism, and Asperger syndrome. "Furthermore, a significant association of the MKL2/MRTFB gene with autism spectrum disorder (ASD) and a de novo mutation of the MKL2/MRTFB gene, which caused an amino acid substitution in a patient with ASD, were reported." (PMID 34795561, 2021).
breast carcinoma (3 papers, 2015 to 2023). "MRTFA was enriched in BLBC and was positively correlated with MaSC/progenitor cell signature and IL6 expression, whereas MRTFB was enriched in luminal-type breast cancer and was negatively correlated with MaSC/progenitor cell signature and IL6 expression." (PMID 26671411, 2015).
left ventricular noncompaction (2 papers, 2020 to 2022). Left ventricular noncompaction (LVNC) is a rare cardiomyopathy characterized anatomically by prominent left ventricular trabeculae and deep intratrabecular recesses causing progressive systolic and diastolic dysfunction, conduction abnormalities, and occasionally thromboembolic events. "This combination involves three heterozygous variants in the genes ΜΥΗ7, MRTFB (MKL2 in the publication) and NKX2-5 identified in a family with left ventricular noncompaction (LVNC), with a suggested Monogenic plus modifier oligogenic effect." (PMID 35411390, 2022).
atherosclerosis (1 paper, 2021). A disease characterized by the build-up of fatty material and calcium deposition in the arterial wall resulting in partial or complete occlusion of the arterial lumen. "It has been previously shown that MRTFA and its related family members MRTFB and myocardin are regulated in vascular injury and atherosclerosis models." (PMID 33597582, 2021).
colorectal cancer (1 paper, 2022). A primary or metastatic malignant neoplasm that affects the colon or rectum. "SPDL1 was defined as a candidate tumor suppressor in colorectal cancer (CRC) to play an essential role in the downstream of Myocardin-related transcription factor B (MRTFB) that could regulate CRC growth and survival." (PMID 35093072, 2022). "A previous study reported that SPDL1 was a tumor suppressor gene for colorectal cancer (CRC), which acted in the downstream of MRTFB to regulate CRC growth." (PMID 35093072, 2022).
leukemia (1 paper, 2021). A malignant (clonal) hematologic disorder, involving hematopoietic stem cells and characterized by the presence of primitive or atypical myeloid or lymphoid cells in the bone marrow and the blood. "MKL/MRTF molecules, MKL1/MRTFA [also termed megakaryocytic leukemia (MAL), basic, SAP, and coiled-coil domain (BSAC)] and MKL2/MRTFB (also termed MAL16), were identified following the discovery of myocardin." (PMID 34795561, 2021).
melanoma (1 paper, 2022). A malignant, usually aggressive tumor composed of atypical, neoplastic melanocytes. "JQ1 was characterized by induction of inhibitory relationship linking regulators of inflammation (IFNG, IL17A, TGFB2), melanoma biological behavior (EGFR, WNT3A, TEADs, MRTFB), cell-cell interaction (CD44, CCN2), YAP pathway (LLGL2, NSUN6) and main transcriptional regulators (FOS, JUN, FOXM1)." (PMID 36397155, 2022).
oral cancer (1 paper, 2024). "In addition, several downstream targets of these specific microRNAs were upregulated by all oral cancer cell lines, such as MBTD1 and FSCN1, or downregulated in all cell lines, such as CLCN3, FLI-1, MRTFB, DAB, SRGAP1, and ABHD17C." (PMID 38396844, 2024).
tumor (9 papers, 2008 to 2025). "RREB1::MRTFB fusion-positive extra-glossal mesenchymal neoplasm is a recently recognized tumor so far mostly described in the head and neck area and in the mediastinum." (PMID 41449216, 2025). "Ectomesenchymal chondromyxoid tumor (ECT) (aka RREB1::MRTFB-rearranged neoplasm) is a tumor of uncertain malignant potential located predominantly in the tongue and arising exceedingly rarely in extraglossal locations." (PMID 38491228, 2024). "This tumor is characterized in most cases by a RREB1::MRTFB fusion, while there is EWSR1 gene rearrangement in a smaller subset of cases." (PMID 38491228, 2024). "Recently, neoplasms carrying the RREB1::MRTFB fusion and showing a variable morphological and immunophenotypic overlap with glossal ECT have been reported from diverse head and neck as well as from non-head and neck sites." (PMID 38491228, 2024).
neurological diseases (1 paper, 2024). "Indeed, lncRNA-SNHG14, MRTFA, and MRTFB play crucial roles in neurological diseases as activators of sero-response factors that regulate related target genes." (PMID 38807051, 2024).
MRTFB also shares sentences with these, for which no sentence is quoted: cancer (8 papers); glaucoma (3); microcephaly (3); cardiac hypertrophy (2); schizophrenia (2); alveolar rhabdomyosarcoma (1); cardiac disease (1); congenital heart disease (1); ependymoma (1); epilepsy (1); fibrosis (1); infection (1); lipoma (1); Lissencephaly (1); lupus nephritis (1); mild cognitive impairment (1); neurodevelopmental disorder (1); renal fibrosis (1); rhabdomyosarcoma (1); sarcoma (1); temporal lobe epilepsy (1); viral infection (1).